MLN (motilin)
Description:
Plays an important role in the regulation of interdigestive gastrointestinal motility and indirectly causes rhythmic contraction of duodenal and colonic smooth muscle.
Tractability: Antibody: its Gene Ontology location is reachable by antibodies, with high confidence; UniProt places it where antibodies can reach, with medium confidence; UniProt predicts a signal peptide or a membrane-spanning region. PROTAC: a small molecule that binds it is known.
Gene: Protein-coding gene on chromosome 6 (33,794,673 to 33,804,003, reverse strand). Ensembl gene ENSG00000096395.
Subcellular location: Secreted
Pathways (Reactome):
Signal Transduction: G alpha (q) signalling events; Peptide ligand-binding receptors
Gene Ontology:
Molecular function: motilin receptor binding; protein binding; hormone activity
Biological process: signal transduction
Cellular component: extracellular region
Genetic constraint (gnomAD): Loss-of-function variants: 5 observed, 6.16 expected, observed/expected ratio (o/e) 0.81, 90% interval 0.42 to 1.63. That is too few expected variants to judge how well the gene tolerates losing a copy. Missense variants: 95 observed, 91.21 expected, observed/expected ratio (o/e) 1.04, 90% interval 0.88 to 1.24. Synonymous variants: 47 observed, 34.63 expected, observed/expected ratio (o/e) 1.36, 90% interval 1.07 to 1.73.
Homologues: Orthologues: chimpanzee MLN (96% identical), macaque MLN (90% identical), pig MLN (77% identical), dog MLN (75% identical), guinea pig MLN (63% identical).
Diseases named in the same sentence as MLN in open-access papers:
MLN is named in the same sentence as 63 diseases in open-access papers, as found by Europe PMC text mining. Sharing a sentence is not in itself a finding about the gene and the disease. The quoted sentences say what the papers report.
Constipation (12 papers, 2010 to 2024). Infrequent or difficult evacuation of feces. "While direct administration of SCFAs does not appear to affect the motilin levels, administration of a dietary symbiotic was associated with concurrent increases in the levels of motilin and gut SCFAs in an animal model of constipation, which correlated with improvements in bowel functioning." (PMID 34575041, 2021). "In a rat model of loperamide-induced constipation, probiotic administration increased the fecal water content and intestinal motility by modulating gastrointestinal peptides such as motilin, vasoactive intestinal peptide (VIP), and AQP3." (PMID 38612481, 2024). "It suggested gut microbial metabolites affected secretion of motilin to increase gastrointestinal movement and transportation function and thus improved pathological symptoms of mice with constipation." (PMID 36016793, 2022). "In contrast, the administration of prebiotics resulted in increases in motilin levels in an animal model of constipation." (PMID 34575041, 2021). "A recent study reported that some GI peptides, particularly neurotensin and motilin, are linked to impaired colonic motility in STC constipation." (PMID 31737065, 2019). "Studies have reported that GI hormones such as motilin (MTL), cholecystokinin (CCK), gastrin (Gas), and SP are significantly decreased while SS and VIP are increased in constipation-induced rats." (PMID 36145085, 2022). "Effect of various samples on serum MTL (motilin), Gas (gastrin), ET (endothelin), SS (somatostatin), AchE (acetylcholine enzyme), SP (substance P) and VIP (vasoactive intestinal peptide) levels in activated carbon-induced constipation model mice." (PMID 25464378, 2014). "Regulation of gastrointestinal hormones, such as cholecystokinin (CCK), gastrin (GAS), somatostatin (SS) and motilin (MTL), may also be another important mechanism for improving the symptoms of LOP-induced constipation in animal models after ACCE administration." (PMID 35518898, 2019).
dyspepsia (6 papers, 2016 to 2024). An uncomfortable, often painful feeling in the stomach, resulting from impaired digestion. "Studies have shown that Aurantii fructus can increase the secretion of motilin, gastrin, and vasoactive peptide substances, relieve gastrointestinal motility disorders, regulate intestinal flora in rats with dyspepsia, promote the growth of beneficial bacteria, and thus treat FD." (PMID 38495103, 2024). "The primary outcome will be the total clinical effective rate and secondary outcomes will include gastrointestinal symptom scale, visual analog scale, FD-related quality of life, electrogastrography, plasma motilin, dyspepsia-related symptom score, gastric emptying, and adverse events." (PMID 31145294, 2019). "The outcome parameters were total clinical efficacy rate (TCE), motilin level, symptom checklist-90-revised (SCL-90-R), and visual analog scale (VAS) for dyspepsia and adverse events." (PMID 37274096, 2023). "Effect of different doses of hesperidin on serum motilin (MTL) and gastrin (GAS) contents in functional dyspepsia rats." (PMID 36034863, 2022).
Obesity (5 papers, 2021 to 2025). Accumulation of substantial excess body fat. "The intravenous infusion of motilin or the motilin receptor agonist erythromycin induces antral contractions and hunger sensations in lean volunteers and volunteers with obesity." (PMID 37836548, 2023). "Moreover, this research group recently published a review that elaborated the role of motilin as a regulator of hunger and food intake in humans, which indicates motilin as a possible target in combating the obesity epidemic." (PMID 33559026, 2021). "In enteroids from patients with obesity, 58 ± 12% of GHRL+ cells co-localized with MLN+ cells, while no co-localization was found between GHRL+ and GLP-1+ cells." (PMID 38125020, 2023).
eosinophilia (4 papers, 2023 to 2026). "Myeloid/lymphoid neoplasms with eosinophilia and tyrosine kinase gene fusions (MLN-TK) are a class of fusion protein-driven, poor prognosis leukemias." (PMID 40881645, 2025). "The ETV6::ABL1 fusion was recently included in the genetic abnormalities defining the disease category of myeloid/lymphoid neoplasms with eosinophilia and tyrosine kinase gene fusions (MLN-TK)." (PMID 39066837, 2024). "A separate category in the WHO classification is the myeloid/lymphoid neoplasms with eosinophilia and tyrosine kinase fusion genes (MLN-TK), which are usually prominent features at diagnosis." (PMID 37274287, 2023). "The MLN-TK with ETV6::ABL1 shares common clinicopathological features with chronic myeloid leukemia, such as eosinophilia and response to tyrosine kinase inhibitor (TKI) therapy, due to the structural and functional similarity of the fusion proteins." (PMID 39066837, 2024). "The information provided by cytogenetic, mutational, and cytologic analysis justifies that CEL represents an independent MPN, which often presents with organ involvement due to eosinophilia, and may share clinical features with PDGFRA-FIPL1 MLN-TK." (PMID 37274287, 2023).
Anxiety (3 papers, 2021 to 2026). Intense feelings of nervousness, tension, or panic often arise in response to interpersonal stresses. "Motilin, as well as the motilin agonist erythromycin, increases GABAergic transmission in this area, resulting in reduced anxiety-like responses to stress." (PMID 34575041, 2021).
gastroparesis (3 papers, 2018 to 2024). Paralysis of the muscles of the stomach wall resulting in delayed emptying of the gastric contents into the small intestine. "Motilin agonist (camicinal) and ghrelin agonist (relamorelin) are new targets under development for gastroparesis, especially in diabetic people." (PMID 32761955, 2020).
irritable bowel syndrome (3 papers, 2020 to 2025). Irritable bowel syndrome (IBS) is a chronic functional condition of the lower gastrointestinal (GI) tract characterized by abdominal pain or discomfort and disordered bowel habit (diarrhea, constipation, or fluctuation between the two). "Studies of irritable bowel syndrome or functional diarrhea have shown abnormal levels of motilin and water content of feces, which are reverted by therapeutic intervention." (PMID 33246492, 2020). "The secretion of substance P (SP) and vasoactive intestinal polypeptide (VIP) are decreased, motilin and cholecystokinin (CCK) are increased after treatment with electrical acupuncture (EA) in rats with irritable bowel syndrome (IBS)." (PMID 32631387, 2020).
acid reflux (2 papers, 2013 to 2025). "The aims of this study in PL were to investigate the prevalence of acid reflux in the proximal oesophagus and functional gastrointestinal symptoms, to analyse motilin levels in plasma, and to assess health-related quality of life (HRQOL) before and after treatment." (PMID 24015952, 2013).
Chronic constipation (2 papers, 2008 to 2019). Constipation for longer than three months with fewer than 3 bowel movements per week, straining, lumpy or hard stools, and a sensation of anorectal obstruction or incomplete defecation. "Chronic constipation has been shown to result from chronic inflammation such as in Chagas disease and has also been shown to be associated with certain peptide deficiencies such as motilin and substance P37." (PMID 30979947, 2019). "Reduced plasma motilin concentration has been reported in adults with chronic constipation." (PMID 18718006, 2008).
colitis (2 papers, 2018 to 2023). Inflammation of the colon. "In this study, we show that T cell intrinsic mPGES-1 deficiency confers partial protection from colitis development, and this is associated with increased RORγt-expressing cells in the mLN and cLP." (PMID 30619314, 2018). "Our previous articles reported that Rap1 deficiency caused lymphopenia in mLN and the reduction in the differentiation of RORγt+ Treg, which led to the expansion of Th17 cells in the LILP and development of colitis." (PMID 39132043, 2023).
depression (2 papers, 2021 to 2026). "The preponderance of evidence suggests that elevated motilin levels are correlated with processes or events that are opposed to depression, while low or dysregulated levels of motilin seem to be associated with processes related to depression, such as chronic stress and unhealthy dietary practices." (PMID 34575041, 2021). "Though caution is required in applying these findings to human subjects, they suggest that depression resulting from chronic stress may be associated with reduced levels of motilin." (PMID 34575041, 2021). "Thus, variations in the release or activity of motilin, mediated through genetic variants, may interact with multiple environmental factors in influencing the risk of depression." (PMID 34575041, 2021). "Finally, in an animal model of chronic stress—the “forced swimming test” (FST), which is used to model depression—rats exposed to the FST showed reduced motilin levels, which were associated with both depression-like behavioral changes and reduced gastrointestinal motility." (PMID 34575041, 2021). "Socioeconomic and cultural factors are key influencers of stress, stress sensitivity and resilience, and altered patterns of motilin release in response to acute and chronic stress may influence susceptibility to depression at the individual and population levels." (PMID 34575041, 2021). "Testing these drugs in animal models of depression would further refine our understanding of the links between motilin and mood." (PMID 34575041, 2021). "The possible link between diet and motilin—and in particular with sugar consumption—represents another possible area of interaction that is relevant to the development of depression." (PMID 34575041, 2021). "Despite the similarities between motilin and ghrelin, there is little research in the literature examining a possible link between motilin and depression in humans." (PMID 34575041, 2021). "In contrast, in a study of patients with depression receiving tricyclic antidepressants at therapeutic doses, significant elevations in basal plasma motilin were observed." (PMID 34575041, 2021). "When considering the potential relationship between the motilin gene and cross-national variations in depression, it is instructive to consider the factors that are commonly cited as underlying these variations." (PMID 34575041, 2021). "Despite the limitations enumerated above, the possibility of a link between motilin and several key physiological processes related to depression is biologically plausible and supported by the limited evidence available to date." (PMID 34575041, 2021). "In this paper, the potential role of gut hormones as potential treatments or predictors of response in depression is examined, with specific reference to the peptide hormone motilin." (PMID 34575041, 2021). "There is evidence for direct or indirect links between motilin and several mechanisms relevant to depression and antidepressant drug responses, though much of this evidence has emerged from experimental research or single-human studies and requires verification and replication in clinical settings." (PMID 34575041, 2021). "Though the exact neurotransmitters mediating this response have not been identified, this finding provides further evidence of the central effects of motilin on the brain circuits involved in appetitive and hedonic behaviors, whose functioning is altered in patients with depression." (PMID 34575041, 2021). "For example, there is preliminary evidence of interactions between motilin and the composition of the gut microbiota and between the levels of motilin and the peptide transmitter neuropeptide Y, which has also been identified as having a protective effect against depression." (PMID 34575041, 2021). "The available evidence seems to suggest an inverse relationship between motilin and depression, though it is likely that this association will not follow a simple linear pattern." (PMID 34575041, 2021).
depression (continued). "Though a definitive conclusion cannot be drawn from this data, there are possible correlations between the FSH, LH, progesterone and motilin levels which may be of relevance to depression, particularly in women." (PMID 34575041, 2021). "Though it is not possible to draw definitive conclusions from this evidence, it is likely that a more in-depth understanding of the functions of motilin in gut–brain signaling, both in healthy subjects and in patients with depression, would emerge from further human and animal studies." (PMID 34575041, 2021). "It was observed that there was a significant negative correlation between the MLN rs2281820 C allele frequency and the estimated prevalence of depression, as well as a positive correlation between the distance from the equator and the prevalence of depression." (PMID 34575041, 2021). "A key question for future research in this field is whether these reported associations are epiphenomenal or whether alterations in central or peripheral motilin play a more direct role in depressive disorders." (PMID 34575041, 2021). "In an animal model of depression using the forced swimming test, rats exposed to this chronic stressor showed significant decreases in the plasma levels of both BDNF and motilin, which occurred in parallel with increases in CRH and cortisol." (PMID 34575041, 2021). "The mechanisms reviewed above may not exhaust all the possible links between motilin and depression." (PMID 34575041, 2021). "The relationship between antidepressant use, symptomatic response and plasma motilin levels may also merit further examination, both as a marker of response and as a potential means of distinguishing responders and non-responders to drug treatment in depression." (PMID 34575041, 2021). "These indirect links between motilin and BDNF require examination in human subjects with and without depression." (PMID 34575041, 2021).
gastric cancer (2 papers, 2016 to 2025). A primary or metastatic malignant neoplasm involving the stomach. "This implied that the MDK-NCL signaling plays a key role in MLN and may contribute to the spread of gastric cancer." (PMID 41249133, 2025).
Hyperglycemia (2 papers, 2013 to 2021). An increased concentration of glucose in the blood. "Hyperglycemia can inhibit the secretion and release of motilin." (PMID 23782501, 2013).
Anorexia (1 paper, 2025). Lack of desire to eat (loss of appetite). "In recent years, imbalance between gastrointestinal peptides such as acyl-ghrelin, motilin and NPY, and anorectic peptides such as pro-opiomelanocortin has been implicated as a cause of CINV and anorexia in cancer patients." (PMID 40045433, 2025). "Motilin is a peptide hormone that is secreted during fasting, and if anorexia occurs after chemotherapy, motilin secretion would be excessive and cause nausea." (PMID 40045433, 2025). "CINV is associated with excessive secretion of motilin and anorexia is related to sustained elevation of leptin, suggesting the potential of these peptides as quantitative indicators of CINV and anorexia." (PMID 40045433, 2025). "This study comprehensively evaluated the changes in blood levels of five gastrointestinal peptide: substance P, neuropeptide (NPY), motilin, ghrelin and leptin, following chemotherapy, and the relationship between these peptides and CINV or anorexia." (PMID 40045433, 2025). "In addition, although there are no reports of a correlation between albumin and motilin concentrations, when anorexia is accompanied by hunger, motilin is overproduced, which also leads to nausea." (PMID 40045433, 2025). "The small sample size may have resulted in insufficient statistical power to detect significant differences in plasma levels of peptides other than motilin and leptin between CINV and non-CINV groups, and between anorexia and non-anorexia groups." (PMID 40045433, 2025).
autonomic dysfunction (1 paper, 2018). "Abnormal gastrointestinal peptide release due to autonomic dysfunction (including pancreatic polypeptide, motilin) causes additional motility and secretory dysfunctions that result in abnormal carbohydrate absorption." (PMID 29725320, 2018).
Burkitt lymphoma (1 paper, 2024). A rare form of malignant mature B-cell non-Hodgkin lymphoma. "Additionally, loss of function GNA13 mutations are enriched in Burkitt lymphoma (BL), which is defined by MYC translocations and commonly presents with mLN involvement." (PMID 39025963, 2024).
colon cancer (1 paper, 2024). "Moreover, in a clinical study of open surgery for colon cancer, patients undergoing intravenous anesthesia involving dexmedetomidine had a quicker recovery of gastrointestinal motility, and the levels of prokinetic gastrointestinal hormones such as motilin and gastrin in the plasma increased." (PMID 39758778, 2024).
colorectal cancer (1 paper, 2021). A primary or metastatic malignant neoplasm that affects the colon or rectum. "An alternate mechanism that may link stress and motilin is the sympathetic nervous system, as a stellate ganglion block has been found to reduce cortisol levels and increase motilin levels in patients undergoing laparoscopic surgery for colorectal cancer." (PMID 34575041, 2021).
diabetes (1 paper, 2017). "Though human and rodent studies confirmed the proportion changes of immune cells in gut LP of diabetic mice, the transplantation of MLN can transmit diabetes to the recipient mice, which highlights the vital pathogenic effects of MLN." (PMID 28217099, 2017).
duodenal ulcer (1 paper, 2015). An ulcer in the duodenal wall. "Additionally, studies have also shown that motilin can induce gastric contraction after inhibition of gastric acid secretion by famotidine (an H2 receptor antagonist) in a patient with duodenal ulcers." (PMID 26115342, 2015).
gastric diseases (1 paper, 2021). "These pathways constitute the molecular mechanism by which motilin regulates LGA blood flow under physiological conditions, and these data may serve as the basis for understanding and treating gastric diseases." (PMID 34777026, 2021).